TM4SF1 (transmembrane 4 L six family member 1)
Diseases named in the same sentence as TM4SF1 in open-access papers (continued):
Sharing a sentence is not in itself a finding about the gene and the disease.
esophageal cancer (6 papers, 2017 to 2024). A primary or metastatic malignant neoplasm involving the esophagus. "In esophageal cancer stem-like cells, downregulation of miR-141 increases TM4SF1 expression, self-renewal ability and promotes cell invasion." (PMID 32000679, 2020). "TM4SF1 is known to promote the self-renewal of esophageal cancer stem-like cells, which is regulated by miR-141; therefore, it was defined as a prognostic marker of squamous carcinomas." (PMID 29254164, 2017). "To investigate the critical role of miR-141-TM4SF1 regulation in esophageal cancer stem-like cells in detail, we transfected pENTER-TM4SF1 plasmid and miR-141 inhibitor into the lenti-miR-141 cells to rescue the TM4SF1 expression." (PMID 27974706, 2017). "TM4SF1 and miR-141 together played important roles in maintaining the self-renewal ability and carcinogenicity of esophageal cancer stem-like cells." (PMID 27974706, 2017). "Regulation of TM4SF1 by miR-141 played an important role in controlling the cell proliferation and self-renewal of esophageal cancer stem-like cells." (PMID 27974706, 2017). "So far, one study demonstrates that miR-141-mediated upregulation of TM4SF1 could stimulate self-renewal of esophageal cancer stem-like cells, suggesting the potential involvement of TM4SF1 in EC malignancy." (PMID 35835740, 2022). "miR-141 was also down-regulated in SP of ESCC cell lines and overexpression of miR-141 could abolish the self-renewal ability and carcinogenicity of esophageal cancer stem-like cells by suppressing the expression of TM4SF1." (PMID 29721170, 2018). "TM4SF1 has been reported to be associated with many tumors invasion and metastasis, but has not been reported in esophageal cancer." (PMID 27974706, 2017). "Studies have reported that TM4SF1 is over-expressed in many malignancies, but the expression profiles of TM4SF1 in esophageal cancer remains unclear." (PMID 27974706, 2017). "TM4SF1 could stimulate the self-renewal ability and carcinogenicity of esophageal cancer stem-like cells, and promote cell invasion and migration." (PMID 27974706, 2017). "Given the fact that we previously showed cancer stem-like cells of ESCC cells were more resistant to anticancer drugs, our results indicated that TM4SF1 could increase the resistant ability of esophageal cancer stem-like cells." (PMID 27974706, 2017). "We also found that overexpression of miR-141 could abolish the self-renewal ability and carcinogenicity of esophageal cancer stem-like cells and decrease cell invasion and migration by suppressing TM4SF1." (PMID 27974706, 2017). "As miR-141 and TM4SF1 were inversely expressed in SP cells, we explored TM4SF1 is a direct target gene of miR-141 and miR-141 could contribute to the self-renewal of esophageal cancer stem-like cells by suppressing TM4SF1." (PMID 27974706, 2017). "The regulation of TM4SF1 by miR-141 may play an important role in controlling self-renewals of esophageal cancer stem-like cells." (PMID 27974706, 2017).
glioma (6 papers, 2018 to 2023). A benign or malignant brain and spinal cord tumor that arises from glial cells (astrocytes, oligodendrocytes, ependymal cells). "Lower pathological grade, macroscopic total resection, younger age, higher Karnofsky performance score, and lower TM4SF1 expression were associated with longer overall survival of patient with glioma." (PMID 33015133, 2020). "One study reported that TM4SF1 was upregulated in glioma tumor tissues and cell lines and that TM4SF1 expression was inversely correlated with patient survival." (PMID 37728418, 2023). "LINC02308 was significantly overexpressed in glioma and acts as a sponge to express miR-30e-3p to up-regulate TM4SF1 and promote glioma occurrence." (PMID 36869083, 2023). "TM4SF1 has been shown to be overexpressed in many malignant tumors, including gliomas; malignant melanomas; and liver, prostate, breast, pancreatic, bladder, colon, lung, gastric, ovarian, and thyroid cancers." (PMID 33015133, 2020). "In human glioma, the expression level of TM4SF1 was markedly higher in higher-grades (III–IV) glioma tissues than in lower grade (I–II) tumor tissues." (PMID 33015133, 2020). "TM4SF1 expression and world health organization (WHO) grades (WHO grades for glioma patients are the gold standard for determining prognosis and the tumors are graded into four malignancy grades." (PMID 33015133, 2020).
non-small cell lung carcinoma (6 papers, 2016 to 2024). A group of at least three distinct histological types of lung cancer, including non-small cell squamous cell carcinoma, adenocarcinoma, and large cell carcinoma. "Previous studies have linked TSPAN27 and TM4SF1 with the occurrence of PTC, and TM4SF1 was reported to be a useful biomarker in the diagnosis and treatment of non-small cell lung cancer." (PMID 36568979, 2022). "We investigated the roles of TM4SF1 in non-small-cell lung cancer progression, particularly in the regulation of chemo-sensitivity." (PMID 31142317, 2019).
lymph node metastasis (4 papers, 2020 to 2024). "More specifically, TM4SF1 methylation was associated with tumor grade and lymph node metastasis." (PMID 38206300, 2024). "High TM4SF1 expression is positively correlated with T classification, lymph node metastasis and predicts an unfavourable prognosis for CRC patients." (PMID 33153498, 2020). "In addition, samples of CRC with lymph node metastasis showed higher B7-H3 and TM4SF1 expression than those without lymph node metastasis." (PMID 33958586, 2021).
melanoma (4 papers, 2010 to 2024). A malignant, usually aggressive tumor composed of atypical, neoplastic melanocytes. "B16F10 mouse melanoma tumor cells express high levels of TM4SF1 and we have noted reduced cell growth, proliferation and migration when TM4SF1 expression was knocked down in cultures in vitro (unpublished data)." (PMID 38946725, 2024). "Experiments conducted in mice showed that the chL6 antibody caused antibody-dependent cellular cytotoxicity at a significantly lower concentration than that required for the mouse and it was even effective against melanoma expressing low levels of TM4SF1." (PMID 33015133, 2020). "Two models, the B16F10 melanoma tumor model syngeneic to the C57BL/6 mouse strain and a cutaneous mouse ear wound model, were employed to study the effects of TM4SF1 in tumor growth and wound healing using Tm4sf1 +/− mice." (PMID 38946725, 2024).
breast tumor (3 papers, 2015 to 2023). "Among estrogen-regulated genes, progestin/PR-A counter-regulated a distinctive subset, including breast tumor progression genes (e.g., HES1, PRKCH, ELF5, TM4SF1), leading to invasiveness." (PMID 26356672, 2015).
esophageal squamous cell carcinoma (3 papers, 2017 to 2024). Esophageal squamous cell carcinoma (ESCC) is a type of esophageal carcinoma (EC) that can affect any part of the esophagus, but is usually located in the upper or middle third. "According to reports, TM4SF1 has the ability to enhance the metastasis of esophageal squamous cell carcinoma by forming a connection with integrin α6." (PMID 38762481, 2024). "Previously we found TM4SF1 gene was highly expressed in side population (SP) cells from esophageal squamous cell carcinoma (ESCC) cell lines, but the role and underlying mechanism of TM4SF1 in ESCC remain unclear." (PMID 27974706, 2017). "However, the function and mechanism of TM4SF1 in esophageal squamous cell carcinoma (ESCC) metastasis remains unclear." (PMID 35835740, 2022).
glioblastoma (3 papers, 2016 to 2026). The most malignant astrocytic tumor (WHO grade IV). "The transmembrane protein TM4SF1 is overexpressed in many cancers and in the tumor vascular endothelium with its level correlating with poor prognosis in glioblastoma." (PMID 27144453, 2016).
malignant pleural mesothelioma (3 papers, 2019 to 2022). A malignant neoplasm that arises from mesothelial cells in the pleura and shows a diffuse growth pattern. "Moreover, Studies have shown that TM4SF1 could serve as a predictor of post-surgical treatment efficacy in patients with malignant pleural mesothelioma (MPM), and patients with higher TM4SF1 expression levels have relatively good prognosis." (PMID 33015133, 2020).
thyroid cancer (3 papers, 2007 to 2020). "TM4SF1 was also suggested as a possible marker of stem-like cells in thyroid cancer cells." (PMID 18034892, 2007).
benign ovarian tumors (2 papers, 2019 to 2022). "This study showed that TM4SF1 was localized in the cell membrane or the membrane of cells near the basement membrane in normal ovarian epithelial tissues and benign ovarian tumor tissues." (PMID 30876464, 2019). "TM4SF1 expression was observed in the cell membrane or the membrane of cells near the basement membrane in normal ovarian epithelial tissues and benign ovarian tumor tissues; however, the expression was mainly concentrated in the cytoplasm in cancer tissues." (PMID 30876464, 2019). "Similarly, the positive expression rate of TM4SF1 protein in OC tissues was higher than that of benign ovarian tumors and normal ovarian epithelial tissues, which may be associated with the abnormal proliferation of ovarian epithelial cells and malignant transformation." (PMID 34995016, 2022).
brain hemorrhage (2 papers, 2024). "Tm4SF1-heterozygous embryos are smaller in body size during early embryonic development, and almost half die in utero due to intracranial hemorrhage in the intraventricular and subarachnoid space, which becomes apparent by E17.5." (PMID 39590375, 2024). "Abnormalities in Tm4sf1-heterozygous embryos were clearly noted starting at about E14.5, when many developed brain hemorrhage." (PMID 39590375, 2024). "Tm4SF1‐heterozygous embryos are smaller in body size during early embryonic development and almost half die in utero due to intracranial hemorrhage; the remaining half are born alive without apparent physiological defects." (PMID 38946725, 2024).
ischemic stroke (2 papers, 2023 to 2024). A stroke disorder caused by obstruction of blood flow to the brain, due to thrombotic (local blood clot formation) or embolic (due to a blood clot or other material traveling from another site) event. "Tm4sf1, an A2 marker involved in cell development regulation, activation, growth, and motility, is upregulated following ischemic stroke compared to sham astrocytes and further increased by NPD1 and RvD1." (PMID 37270727, 2023).
lung adenocarcinoma (2 papers, 2007 to 2019). A carcinoma that arises from the lung and is characterized by the presence of malignant glandular epithelial cells. "In the present study, we found some genes that are related to drug resistance, such as AKR1C1/C2 and NR0B1, or cancer metastasis, such as TM4SF1, were up-regulated in SP cells of human lung adenocarcinoma A549 cell line." (PMID 18034892, 2007).
oral submucous fibrosis (2 papers, 2022 to 2025). "Another microRNA involved in EMT regulation is miR-203, a significantly upregulated microRNA in oral submucous fibrosis compared to normal oral mucosa, which can become a decisive factor for malignant transformation of oral submucous fibrosis by targeting SFRP4 and TM4SF1." (PMID 41303164, 2025).
pancreatic ductal adenocarcinoma (2 papers, 2015 to 2022). An infiltrating adenocarcinoma that arises from the epithelial cells of the pancreas. "TM4SF1 is overexpressed in pancreatic ductal adenocarcinoma (PDAC) and affects the development of this cancer." (PMID 26709920, 2015).
papillary thyroid carcinoma (2 papers, 2022). "The upregulation of transmembrane 4 L six family member 1 (TM4SF1) in papillary thyroid carcinoma patients is associated with lymph node metastases." (PMID 36249071, 2022).
triple-negative breast carcinoma (2 papers, 2020 to 2022). An invasive breast carcinoma which is negative for expression of estrogen receptor (ER), progesterone receptor (PR), and human epidermal growth factor receptor 2 (HER2). "However, TM4SF1-siRNA transfection results in the opposite phenomenon in the triple-negative breast cancer (ER-/PH-/HER2-) cell line MDA-MB-231." (PMID 35153775, 2022).
asthma (1 paper, 2022). "The AUC value of FKBP5 (AUC = 0.832), WNT5A (AUC = 0.813), TM4SF1 (AUC = 0.769), PDK4 (AUC = 0.753), EPAS1 (AUC = 0.748) and GMPR (AUC = 0.705) was more than 0.7, which suggesting higher diagnostic value for asthma." (PMID 36550577, 2022). "FKBP5, WNT5A, TM4SF1, PDK4, EPAS1 and GMPR had potential diagnostic value for asthma." (PMID 36550577, 2022).
bladder urothelial carcinoma (1 paper, 2024). "Significantly, knocking down TM4SF1 reduces bladder urothelial carcinoma proliferation, revealing the role of disulfidptosis in bladder urothelial carcinoma and sheds light on its potential regulatory mechanisms." (PMID 38685115, 2024).
Cirrhosis (1 paper, 2023). A chronic disorder of the liver in which liver tissue becomes scarred and is partially replaced by regenerative nodules and fibrotic tissue resulting in loss of liver function. "And than, using SPSS 13.0 statistical software to analyze our data, we found that the expression of TM4SF1 was positively correlated with the tumor size, Edmondson–Steiner grade, and cirrhosis, but not with sex, age of the patients and so on." (PMID 37069693, 2023).
endometrioid adenocarcinoma (1 paper, 2025). An adenocarcinoma characterized by the presence of malignant glandular epithelial cells resembling endometrial cells. "Of particular note is that the expression of TM4SF1 in endometrioid adenocarcinoma is significantly lower than in normal tissues." (PMID 40046734, 2025). "It is noteworthy that TM4SF1 exhibited significantly reduced expression in endometrioid adenocarcinoma compared to normal tissues." (PMID 40046734, 2025).
Insulin resistance (1 paper, 2019). Increased resistance towards insulin, that is, diminished effectiveness of insulin in reducing blood glucose levels. "Ectonucleotide pyrophosphatase/phosphodiesterase 5 (ENPP5), SLC38A1, and TM4SF1 are novel biomarkers for the development of insulin resistance." (PMID 30678306, 2019).
keloid (1 paper, 2025). An irregularly shaped, elevated mark on the skin caused by deposits of excessive amounts of collagen during wound healing. "Its expression is suppressed by miR-1-3p and miR-214-5p, whose downregulation in keloids leads to TM4SF1 overexpression and sustained fibroblast activation." (PMID 41424791, 2025). "TM4SF1 enhances keloid fibroblast proliferation and migration by activating AKT and ERK1/2 signaling." (PMID 41424791, 2025).
metastatic tumor (1 paper, 2025). "The transcriptional regulation of TM4SF1 in stem cells of mesenchymal or cancer origin, or during the epithelial-to-mesenchymal transition into invasive and metastatic tumor cells, remains largely unknown, as is the mechanism of TM4SF1 suppression in most cell types." (PMID 41226530, 2025).
pancreatic adenocarcinoma (1 paper, 2015). "Therefore, we focused on the role of TM4SF1 in pancreatic adenocarcinoma by observing the effects of silencing this gene on the chemotherapeutic agent in vitro and in vivo." (PMID 26709920, 2015).
rectal cancer (1 paper, 2023). A primary or metastatic malignant neoplasm that affects the rectum. "The bulk expression of CSTB and TM4SF1 was associated with both advanced tumor stage and poor PFS time in both colon and rectal cancer patients." (PMID 36816947, 2023).
Stroke (1 paper, 2023). Sudden impairment of blood flow to a part of the brain due to occlusion or rupture of an artery to the brain. "Pan-reactive astrocyte genes (Cxcl10 and Osmr), A1 neurotoxic genes (Amigo2, Ugt1a, Gpc4, H2-D1, and Iigp1), and A2 neuroprotective genes (Ptx3, Thbs2, and Tm4sf1) were all upregulated by NPD1 + RvD1 in the ipsilesional penumbra at 24 h after stroke." (PMID 37270727, 2023).
subarachnoid hemorrhage (1 paper, 2024). A serious neurological disorder characterized by intracranial hemorrhage into the subarachnoid space. "This implies considerable variability among Tm4sf1-heterozygous embryos, with some encountering more severe vascular defects with early lethality, others intraventricular and subarachnoid hemorrhage, or normal development." (PMID 39590375, 2024). "We report that Tm4sf1-null embryos fail to form blood vessels and experience embryonic lethality at E9.5; Tm4sf1-heterozygotes are smaller in size than wild type embryos during early embryonic growth, and half die in utero, often with intraventricular and subarachnoid hemorrhage." (PMID 39590375, 2024). "We anticipate, based on our occasional observations of the end-stage necrosis of Tm4sf1-heterozygous embryos as early as E14.5, that some Tm4sf1-heterozygous embryos may experience lethality before they have developed the apparent intraventricular and subarachnoid hemorrhage seen near birth." (PMID 39590375, 2024).